BRCA1 (BRCA1 DNA repair associated)
Diseases named in the same sentence as BRCA1 in open-access papers (continued):
Sharing a sentence is not in itself a finding about the gene and the disease.
breast cancer (continued). "It is known that BRCA1 mutations lead to worse outcomes in breast cancer and there is data to suggest that BC patients with low BRCA1 expression may have better overall survival and response to treatment." (PMID 34611475, 2021). "According to previous studies, around 40% of BRCA1-related breast cancers belong to ductal carcinoma, not otherwise specified (ductal NOS) type, while typical medullary carcinoma (MC) feature can be observed in 7.8% to 13% of BRCA1-associated breast carcinomas 12-14." (PMID 34815798, 2021). "According to clinical guidelines, the occurrence of very early-onset breast cancer (VEO-BC) (diagnosed ≤ age 30 years) or VEO ovarian cancer (VEO-OC) (diagnosed ≤ age 40 years) in families with BRCA1 or BRCA2 mutation (BRCAm) prompts advancing the age of risk-reducing strategies in relatives." (PMID 34356116, 2021). "Further resolving the function of ID4 in BLBC will require detailed biochemical analysis of DNA repair functional assays, genetic studies with ID4 knockout cells or animals and access to a large cohort of familial breast cancers with detailed gene copy number, BRCA1 mutation and methylation data." (PMID 32527287, 2020). "So far, BRCA1-c.211dupA mutation has been reported only in Tunisian families with breast cancer." (PMID 33240314, 2020). "Ovarian and breast cancers with germline mutations in BRCA1/2 are sensitive to PARPi 9,10." (PMID 32863940, 2020). "Additionally, delivery of EF2K-specific siRNAs into BRCA1-mutated breast cancer in an orthotopic xenograft model by silica-coated cobalt-ferrite nanoparticles considerably diminishes tumor growth and metastasis." (PMID 33287240, 2020). "Finally, the cytotoxicity of olaparib against the BRCA1-deficient MDA-MB-436 breast cancer cells was further significantly enhanced by 2 and 4 μM ATL, suggesting that ATL sensitized cancer cells to olaparib through mechanisms other than inducing HR deficiency." (PMID 32029902, 2020). "Additionally, in the younger patients group, percentage of gene mutations predisposing to breast cancer occurrence, such as breast cancer genes 1 and 2 (BRCA1/2), is higher." (PMID 32645841, 2020). "On screening several vitamin D-sensitive and -resistant breast cancer cell lines, these authors suggested that the sensitivity to the antiproliferative action of 1,25(OH)2D was strongly associated with its ability to modulate BRCA1." (PMID 32456160, 2020). "Developing novel radiosensitivity assays could be a promising approach in evaluating the DNA repair capacity of individuals with BRCA1/2 mutation and consider as a predictive factor for overall increased risk mainly in the relatives of breast cancer patients." (PMID 33013205, 2020). "Targeting the RANKL/RANKL axis may be a rational prevention strategy for patients with BRCA1 mutation-positive breast cancer." (PMID 32047573, 2020). "Among 491 previously unaffected BRCA1/2 mutation carriers enrolled in our study of annual breast screening with MRI and mammography, after a median follow-up of 13 years, there were only four cases of breast cancer-related death." (PMID 33238387, 2020). "Cancer biomarkers such as BRCA1/2 are significant indicators of breast cancer; however, many BRCA1/2 mutations and unknown genetic variants are poorly defined, making disease risk uncertain and disease assessment and diagnosis complicated." (PMID 31991576, 2020). "The observations that BPM was associated with lower mortality rates than surveillance for BRCA1 and similar breast cancer-specific survival for BRCA2, underscore the importance of counseling BRCA1/2 mutation carriers on their choice between breast surveillance and BPM." (PMID 31832891, 2020).
breast cancer (continued). "One example is a point mutation in putative TATA box of 17 beta-hydroxysteroid dehydrogenase 2 (EDH17B2) gene, which has been suggested as a candidate for the familial breast cancer gene together with the breast cancer type 1 susceptibility protein (BRCA1) gene." (PMID 33113880, 2020). "However, in cells exhibiting defective HR, such as breast cancer cells with pathogenic BRCA1/2 mutations, defects cannot be repaired, leading to tumor-specific cell death." (PMID 32300589, 2020). "Moreover, there are other types of cancers related to the BRCA1 mutations, such as fallopian tube and peritoneal cancer in women and prostate and breast cancer in men." (PMID 33013205, 2020). "Nonetheless, the fact that roles other than in HR (i.e., in replication fork stability/recovery) for all three major breast cancer susceptibility genes (BRCA1, BRCA2 and PALB2) have been described, complicates the interpretation of VUS in these genes and their association with cancer risk." (PMID 33195396, 2020). "In addition, we performed Plekha5 knockout in a GFP-labeled mouse Brca1-deficient mammary tumor cell line with low metastatic potential (G600-GFP) and implanted these cells into mice." (PMID 32978388, 2020). "Therefore, we were unable to assess associations with ER-specific breast cancer in the entire sample of BRCA1/2 carriers." (PMID 32665703, 2020). "This may highlight the potential of MAD2L1 to act as a possible therapeutic target not only in BRCA1/2-mutated breast cancer but also in a wider group of patients with a high activity level of this pathway." (PMID 32620799, 2020). "Therefore, the MR results from the selection of genetic variants from the Asian population in our study, as expected, suggested that RA reduces the risk of breast cancer within participants from BRCA1 carriers, which mostly consists of Caucasians." (PMID 33167385, 2020). "Therefore, this study aimed to obtain and evaluate PROs in BRCA1/2 mutation carriers according to their choice of breast cancer risk management (BPM-IBR versus breast surveillance)." (PMID 31832891, 2020). "In the western population, about 5% of the breast cancer patients may carry heritable cancer susceptibility gene mutations, with BRCA1 being the most common mutation." (PMID 32322271, 2020). "For example, application of the NCCN version 2.2017 criteria to a cohort of 1371 newly diagnosed breast cancer patients from Norway who were tested for BRCA1 and BRCA2 mutations, revealed that 32 of 38 (88.9%) mutation carriers would have been classified as high-risk." (PMID 31963545, 2020). "Studies in both mouse models and human tissues have shown that BRCA1-associated breast cancer may arise from aberrant luminal epithelial progenitor cells of the mammary gland, which may endow the cancer triple-negative molecular signature." (PMID 33299637, 2020). "Estimated ratio of BRCA1 germline mutation with respect to inherited breast cancer is 9-17%." (PMID 32856871, 2020). "This open basket study aims to compare the safety and efficacy of durvalumab in combination with the PARPi olaparib or in combination with olaparib plus the VEGF inhibitor bevacizumab in patients with advanced solid tumors including BRCA1/2-deficient breast cancer." (PMID 33718107, 2020). "It is estimated that a total of 5–10% of all breast cancer cases are genetically susceptible to the disease, with multiple breast cancer susceptibility genes having been proposed, including breast cancer 1 (BRCA1) and breast cancer 2 (BRCA2), two of the major genes." (PMID 32509471, 2020). "The literature has documented that women who inherited a deleterious BRCA mutation suffer a high lifetime risk of developing breast cancer, with a large-sized prospective study estimating a cumulative incidence of 66 and 61% for BRCA1 and BRCA2 up to the age of 70 years, respectively." (PMID 33505905, 2020).
breast cancer (continued). "However, there are still some controversies concerning the investigation of breast cancer treatment based on BRCA1 mutations." (PMID 33817238, 2020). "Modifications of BRCA1 are correlated with a high risk of improving breast cancer." (PMID 33273900, 2020). "Therefore, these most likely represent real differences, in which PRS modify breast cancer risk for BRCA1/2 carriers to a smaller relative extent than the general population." (PMID 32665703, 2020). "As mutations in BRCA1 gene also result in an increased risk of breast cancer, our findings may provide important implications for breast cancer prevention in BRCA1mut carriers." (PMID 33227068, 2020). "Moreover, the genomic footprints in BRCA1-mutated breast cancer are distinct from those bearing BRCA2 mutations, implying the involvement of different mutational processes/mechanisms." (PMID 33087072, 2020). "Interestingly, combined PI3K and PARP inhibition have also provided more efficient responses in BRCA1-deficient breast cancer cells and dual ATR and BCR inhibition has also been proven to be synergistic in ATM-defective CLL cells." (PMID 31974435, 2020). "The homologous recombination deficiency (HRD) score was developed using whole-genome copy number data derived from arrays as a way to infer deficiency in the homologous recombination DNA damage repair pathway (in particular BRCA1 or BRCA2 deficiency) in breast cancer samples." (PMID 32818150, 2020). "The identified breast cancer susceptibility genes in the FA pathway, including BRCA1, BRCA2, BRIP1, PALB2, and RAD51C, are essential genes involved in HR, the error-free pathway for DSB repair during physiological cell cycle progression, which repairs replication-associated DNA damage." (PMID 32300589, 2020). "Deleterious germline mutations in the BRCA1 protein have been found to significantly increase the risk of breast cancer and ovarian cancer, up to 72 and 44% respectively by age 80, as well as increased risk of many gastrointestinal, pancreatic and prostate cancers." (PMID 32493233, 2020). "To further evaluate whether BRCA1/2 potentially pathogenic variants could recur in larger sporadic breast cancer cases and/or other cancer types, we designed our own panel with the 20 pathogenic variants above." (PMID 32879886, 2020). "Since HOXB13 p.G84E is a prostate cancer risk allele, we evaluated the association between HOXB13 germline mutations and breast cancer risk in a previous study consisting of 3,270 familial non-BRCA1/2 breast cancer cases and 2,327 controls from the Netherlands." (PMID 32546843, 2020). "Combining the Japanese cases with 34 cases from TCGA breast cancer cases, we tested this hypothesis using a total of 64 cases with germline BRCA1/BRCA2 variants." (PMID 33067557, 2020). "Loss of BRCA1 in epithelial tissues leads to mammary tumors, with long latency and low frequency." (PMID 32053991, 2020). "Indeed, SOX2 is frequently gained in BRCA1 germline mutated tumors and is preferentially expressed in sporadic basal-like phenotypes having similar phenotypic and clinical characteristics to breast cancer arising in BRCA1 mutation carriers." (PMID 32191225, 2020). "Interestingly, we found that Chinese breast cancer patients have more frequent mutations in BRCA2 than in BRCA1 which differ from those in Western breast cancer patients." (PMID 32091409, 2020). "Ongoing trials should clarify whether PARP inhibitors might improve outcome when administered in the adjuvant or neoadjuvant setting in early breast cancer patients with BRCA1/2 mutation or homologous recombination defect." (PMID 32471249, 2020). "The high occurrence and death rates of breast cancer in cancer survivors may likely be attributed to BRCA1 and BRCA2 mutations as well as chemotherapy and radiotherapy for prior cancer." (PMID 32250967, 2020).
breast cancer (continued). "Our study provided a new insight into the dysregulation of glycolysis in breast cancer, which might be partially due to the deficiency of BRCA1/ZBRK1 axis and subsequently reversed the transcriptional repressive effect on PFKP." (PMID 32470015, 2020). "Women with a BRCA1 or BRCA2 gene mutation have up to an 80% lifetime risk of breast cancer unless their breasts are surgically removed, but many decline or defer surgery and choose screening, hoping that if cancer occurs, it will be detected at a curable stage." (PMID 33238387, 2020). "First, the specificity among different cancers might weaken the persuasion of pathogenic variants validated in breast cancer and only focusing on BRCA1/2 exons might miss some potential deleterious variants." (PMID 32879886, 2020). "About 20–25% of hereditary cancers and 5–10% of all breast cancers are caused by BRCA1/2 mutations." (PMID 32033165, 2020). "In breast cancer, carriers of pathogenic BRCA1 or BRCA2 variants are faced with the decision about whether to undergo prophylactic mastectomy as opposed to serial imaging." (PMID 32820175, 2020). "Furthermore, when we overexpressed BRCA1 in HCC1937 cell line (a BRCA1 deficient breast cancer cell line), there was a notable suppression of PFKP expression in both protein and mRNA level upon BRCA1 overexpression." (PMID 32470015, 2020). "BRCA1: p.Ile1845fs variant was a frequently pathogenic mutation in breast cancer in Han Chinese women and our data may be helpful for diagnosis and therapy of breast cancer." (PMID 31908633, 2020). "The majority of BRCA1-associated breast cancers belong to the TNBC subtype." (PMID 32722046, 2020). "RANKL plays a role in the breast cancer development signaling in patients with BRCA1 mutations." (PMID 32318347, 2020). "This characteristic of mammary cells may play a role in tissue-specific carcinogenesis induced by BRCA1 germline mutations, and could explain the high incidence of centrosomal amplification in aggressive breast cancers." (PMID 32722046, 2020). "To date, there are five reviews evaluating the impact of either dietary habits, weight management, or PA, or a combination of only two of these factors (i.e. diet and weight), on ovarian and/or breast cancer risk among women with BRCA1/2 pathogenic germline gene variants from 1997 to 2015." (PMID 32165993, 2020). "The kinetics of XRCC1 foci in the BRCA1-deficient breast cancer cell line MDA-MB-436 are similar to those in U2OS cells and are also sensitive to niraparib treatment, suggesting that BRCA1 does not directly modulate the PAR–dependent, early recruitment of XRCC1." (PMID 32890402, 2020). "Although the frequencies of BRCA1/2 mutations vary significantly in different populations, based on geographic regions and ethnicities, they tend to occur infrequently in most populations; hence, BRCA1/2 genes are classified as rare high-penetrance breast cancer susceptibility genes." (PMID 32300589, 2020). "Thus, miR-381-induced JARID1B downregulation causes hypersensitivity to DNA damage and BRCA1 upregulation, which plays an important role in breast cancer migration." (PMID 33324542, 2020). "Since the NHEJ-promoting function of 53BP1 is inhibited by BRCA1, loss of BRCA1 at DSBs in PRMT1-silenced breast cancer cells may suppress HR and direct DNA repair toward NHEJ." (PMID 32764667, 2020). "And they found the concomitant BRCA1 mutations and gene fusions in breast cancer cells." (PMID 33520689, 2020). "To determine whether there were similar CNV events in both human and mouse breast cancers, we then used the same approach to study CNVs from two human BRCA1-deficient (TM00089 and TM00091) xenograft breast tumors by single-cell and bulk WES." (PMID 32978388, 2020). "We therefore assessed whether there is evidence for copy number change of ID4 in (i) sporadic disease or (ii) in the context of familial breast cancer driven by germline BRCA1 mutation." (PMID 32527287, 2020).
breast cancer (continued). "Although the frequency of mutations in each gene is much lower than BRCA1/2, the collective mutation rate is more than the mutation rate of BRCA1/2 in our cohort, providing important data for non-BRCA1/2 mutations in breast cancer patients in Southern Chinese population." (PMID 32091409, 2020). "BRCA1/2 are well-known tumor suppressor genes whose loss of function mutations are associated with early-onset, increased familial inheritance, sporadic incidence, tumor aggression, and poor outcomes in breast cancer." (PMID 32846967, 2020). "However, little is known about how BRCA1 relates to mitophagy in response to mitochondrial damage and how defects in mitophagy contribute to BRCA1‐associated breast cancer." (PMID 32195105, 2020). "Unsurprisingly, women with inherited pathogenic mutations in BRCA1 or BRCA2 have up to an 85% risk of breast cancer development; hence, risk reduction measures, such as intensive radiological screening, prophylactic surgery, or chemoprevention were suggested for these candidates." (PMID 32300589, 2020). "BRCA1 germline mutations have been found in inherited breast cancer." (PMID 32856871, 2020). "To date, the contribution of BRCA1/2 mutations in Moroccan early onset breast cancer patients remains unknown." (PMID 32894085, 2020). "Importantly, a multinational phase III clinical trial using Denosumab to prevent the development of breast cancer in BRCA1-mutation carriers is currently being initiated." (PMID 32850393, 2020). "We have found that BRCA1: p.Ile1845fs variant is associated with risk of breast cancer." (PMID 31908633, 2020). "Breast cancer patients with BRCA1 mutations are more frequently found to have TNBC." (PMID 32235451, 2020). "Therefore, developing further radiosensitivity assay is still warranted to evaluate the DNA repair capacity of individuals with BRCA1/2 mutations and serve as a predictive factor for increased risk of cancer mainly in the relatives of breast cancer patients." (PMID 33013205, 2020). "There are two very important breast cancer susceptibility genes, BRCA1 and BRCA2." (PMID 32824581, 2020). "Breast cancer with germline mutations in BRCA1 or BRCA2 have been a focus of therapeutic targeting." (PMID 32457830, 2020). "While BRCA1/2 mutations affect a minority of breast cancer patients (fewer than 5%)." (PMID 32974031, 2020). "This is, to our knowledge, the first multistep approach, including regional breast cancer screening program, general practitioners and specialists, aimed to identify individuals with BRCA1/2 mutations and to offer an intensive surveillance program for hereditary, high and intermediate risk women." (PMID 32045136, 2020). "BRCA1/2 mutation carriers face more aggressive surgical interventions for therapeutic and risk reducing purposes due to their high risk of developing primary or contralateral breast cancer." (PMID 33194613, 2020). "Provision of genetic counselling and genetic testing for rare variants in breast cancer predisposition genes such as BRCA1 and BRCA2 can lead to better management of risk, but these only explain a small fraction of breast cancer cases in the general population." (PMID 32737321, 2020). "In many cases breast cancer is caused by mutation in BRCA1 and BRCA2 genes." (PMID 33225921, 2020). "The basal-like breast cancers more frequently have a mutation in the BRCA1 tumor suppressor gene." (PMID 33162807, 2020).